IL6 (interleukin 6)
Diseases named in the same sentence as IL6 in open-access papers (continued):
Sharing a sentence is not in itself a finding about the gene and the disease.
infection (continued). "Seven days after infection, the expression of IL-1β, IL-6, IL-17, IL-18, and TNF-α mRNA was significantly lower in the jejunum of COS-fed mice compared to those of controls." (PMID 28100936, 2016). "Titers of TNF-α, IL-6, IL-12, and IL-4 after infection changed at same level between LI and LM infections." (PMID 27375558, 2016). "The procedure is cytokine driven through IL-6 and others, which responsible for the acute-phase changes usually seen upon infection or injury." (PMID 26799214, 2016). "As regulators of inflammation, monocytes are able to produce pro-inflammatory mediators such as IL-8 (CXCL8), a chemokine that controls the influx of inflammatory and immune cells to sites of injury and infection, and IL-6, a key B cell differentiation factor." (PMID 27391120, 2016). "Studies have shown that TLR3 plays a fundamental role in the expression of proinflammatory cytokines such as IL-6 and IL-1beta in fibroblasts or classical dendritic cells derived from TLR3-deficient mice after infection with NDV." (PMID 26975566, 2016). "But the concentration of IL-1β reached the peak (about 2.6-fold, P > 0.05) in CK/SD/w4 infections, and the IL-6 in CK/SD/w3 infections (about 2.8-fold, P < 0.05)." (PMID 27446066, 2016). "Our results support the notion that in the initial moments of the infection, the IL-6 concentration increased as a response to increase in parasite load and is subsequently controlled by IL-10 secretion as has been discussed for other authors." (PMID 26943639, 2016). "The higher levels of expression of Fgb and IL6 in males compared with females are consistent with the greater vulnerability of males to infection and subsequent inflammation." (PMID 27120355, 2016). "Production of inflammatory cytokines was also observed, with detection of significantly higher production of IL-6 from the 4th day after the third infection." (PMID 26814713, 2016). "Young mice had increased levels of inflammatory cytokines G-CSF, IL-6, and IL-1α, which peaked at 6 dpi and then returned to baseline by day 12 as the infection was resolving." (PMID 27177221, 2016). "During both iron supplementation and infection, we treated the pMacs with either a control antibody or a monoclonal antibody against the IL‐6 receptor‐α subunit 34, 35, to inhibit IL‐6 signaling." (PMID 27980776, 2016). "Compared to uninfected models, ANDV caused long-term elevated levels of eotaxin-1, IL-6, IL-8, IP-10, and VEGF-A that peaked 20–25 days after infection, i.e., after the observed peak in progeny virus production." (PMID 26907493, 2016). "S. pyogenes induced epithelial secretion of both cytokines IL-8 and IL-6 and reached a maximum level at 72 h post infection (**p<0.001) and further declined thereafter (data not shown)." (PMID 27014727, 2016). "Intravenously infected piglets showed a peak production of Interleukin 6 (IL-6) and Interleukin 1 beta (IL-1-β) serum concentrations 1 day post-infection (p <0.001) to decrease to normal levels respectively 3 and 5 days post-infection." (PMID 27276874, 2016). "Quantitative reverse transcription-PCR data showed that 30 min post PAO1 infection, transcriptions of all tested NF-κB-dependent genes, including IL-1α, IL-1β, IL-6, IFN-γ, MCP-2, MIP1α, TNF-α and TLR2, were significantly increased in Lyn-silenced MH-S cells." (PMID 29263906, 2016). "Secondary infection induced a rapid increase in the expression of IL-4, IL-6 and IL-13 from 2 wpsi and beyond." (PMID 27658962, 2016). "During infection, pro-inflammatory cytokines such as interleukin 1B (IL-1B), interleukin 6 (IL-6) and tumor necrosis factor-a (TNF-a) participate in inducing acute-phase reaction including fever." (PMID 26960986, 2016). "On the other hand, the ΔlppAB ΔmsbB mutant-infected mice generally displayed higher levels of serum cytokines during the later stages of infection and IL-6 production from T-cells, as well as more fecal IgA production." (PMID 27891321, 2016).
infection (continued). "At 24 h, tonB K. pneumoniae infection also caused levels of induction of IL-6, CXCL1, CXCL2, IL-1β, and MIP-3α secretion that were comparable to those seen after 48 h of infection with WT K. pneumoniae." (PMID 27624128, 2016). "The expression of IL-6 mRNA in infected VECs peaked at 12 h post-infection, at a level of almost 3.5-fold higher than in the control cells (p < 0.01)." (PMID 27852059, 2016). "Drug cure resulted in a sudden decrease of most of the cytokines that became overexpressed after primary infection (IL-6, IL-9, IL-12, IL-33, IFN-γ and TSLP)." (PMID 27658962, 2016). "Comprehensive cytokine/chemokine analysis reveals a host response to Ft largely similar between LVS and SchuS4 with significant levels of many factors (e.g., TNFα, IL-1β and IL-6) appearing at 3 dpi onwards during infection." (PMID 27015566, 2016). "Exposure of BEAS-2B cells to H. influenzae before and during RSV-infection synergistically increased the release of IL-6 (increase above calculated additive effect at 72 h: 56 % ± 3 %, mean ± SEM) and IL-8 (53 % ± 12 %)." (PMID 27259950, 2016). "Pathway enrichment analyses confirmed that the IL-6 signaling pathway is significantly enriched among temporal post-infection altered genes." (PMID 26865111, 2016). "Interleukin 6 (IL-6) is a multi-functional cytokine produced by a wide range of cell types in the early stages of infection." (PMID 27481356, 2016). "In a parallel study to this work, evaluation of transcripts in whole blood samples revealed that at 3 months post infection, IL-6 signal transducer (ST) gene was upregulated in the MAP-infected calves compared to the control group." (PMID 27065983, 2016). "At 48 and 72 h post infection, mRNA expression of IL-1β, IL-6, IL-8, and TNF-α in mimic-transfected cells was substantially decreased compared to the control mimic." (PMID 27117627, 2016). "In response to infection, pericytes mount an inflammatory response by increasing expression of proinflammatory cytokines, such as IL-6, TNF-α, and IL-1β." (PMID 27143977, 2016). "During the progression of inflammation, proinflammatory cytokines such as TNF-α and IL-6 are released by macrophages to protect the body from tissue injury or infection." (PMID 27890971, 2016). "The M1 macrophages, unlike the M2 macrophages, produce NO and other pro-inflammatory cytokines such as the TNF-α, IL-6 and IL-1β to fight infection." (PMID 26934748, 2016). "Although IL-6 and IL-10 were both secreted in the first hours of infection, IL-10 mainly mediates the activation of STAT3 signaling in infected macrophages." (PMID 27384401, 2016). "In VECs, the IL-6 expression differences appeared from 3 h post-infection and were maintained over the following 22 h." (PMID 27852059, 2016). "Infection led to a further increase in the levels of plasma pro-inflammatory cytokines including IL-6, TNF-α, KC and MIP-2." (PMID 26859674, 2016). "Whereas it is not surprising that a threshold in parasite loads has to be reached before DCs are able to sense infection, it is intriguing that Ei selectively induced IL-6 secretion." (PMID 26870700, 2016). "Based upon our RT-PCR analysis of IL-6, IL-10 and TNFα in macrophages infected with legS2 mutants, we can conclude that infection with L. pneumophila legS2 dampens the mRNA expression of cytokines in infected cells." (PMID 26741365, 2016). "Next, we analyzed the level of proinflammatory cytokines (TNF, IL-6) and nitric oxide (NO), the key components in Leishmania control, in BMDCs cell supernatants 24h post infection." (PMID 27580076, 2016). "Production of IFN-γ, TNF-α, and IL-6 suggests a type-1 proinflammatory response being developed shortly after infection, while IL-10 production can be related to immune regulation." (PMID 26989699, 2016). "After 20 h of infection the supernatant was collected and analysed via an IFNα as well as an IL-6 ELISA." (PMID 27273104, 2016).
infection (continued). "IL-6 and IL-12 are the major cytokines produced by DCs in response to infection by intracellular pathogens." (PMID 27729911, 2016). "Pro-inflammatory cytokines (IFN-γ, IL-18, IL-6, TNF-α) and chemokines (CCL2, CCL5, CCL7, CXCL1, CXCL10) were found to be increased in sera of ZIKV-infected mice, indicating that infection causes systemic inflammation." (PMID 27163257, 2016). "Cortex showed the highest release of CCL2 and IL-6 from both 48 and 72 hpi (hours post infection) compared to other regions." (PMID 26931456, 2016). "For example, plasma IP-10, IL-8, and MCP-1 in RDPs reached peak value at 30 days post infection, whereas IL-6, GM-CSF, and VEGF were delayed after 60 days post infection in RDPs." (PMID 27830756, 2016). "Despite equivalent bacterial loads, infection with tonB K. pneumoniae resulted in increased bacterial dissemination and IL-6, CXCL1, and CXCL2 secretion compared to infection with the entB ybtS tonB mutant." (PMID 27624128, 2016). "Important immune cells required for bacterial clearance are macrophages and neutrophils, which are attracted and activated to sites of infection by IL-8, IL-6, and TNF-α." (PMID 27527221, 2016). "IL-6 production in the lung after LM infection showed an obvious increase up to 9.5 pg/mg total lysate protein at 3 dpi, while the production after LI infection was barely increased." (PMID 27375558, 2016). "At 29 days post-infection following B. melitensis intradermal inoculation, the expression of Il6 was significantly higher compared to intranasal infection." (PMID 28018318, 2016). "Another study showed that a highly virulent H5N1 virus induced antiviral (IFN-α and IFN-β) and proinflammatory (IL-4, IL-6, IL-8, and IL-15) cytokine mRNA expression in the lung at 24 h post infection, which abruptly decreased within the next 8 h." (PMID 27078641, 2016). "IL6 was 10-fold higher in cPLA2α−/− compared to cPLA2α+/+ mice at 6 and 12 h after infection then decreased by 24 h." (PMID 27501951, 2016). "Inhibition of STAT3 signaling during infection led to an increase of the inflammatory cytokine secretion, IL-6 (26 fold) and TNF-α (5 fold), compared to control infected macrophages." (PMID 27384401, 2016). "Expression of the inflammatory cytokines TNF-α and IL-6 is rapidly induced in response to stimulation by antigens, infection, and stress, and are transcriptionally regulated by NF-κB24." (PMID 27625297, 2016). "At the beginning of the chronic phase (29 days post-infection), we observed a strong decrease of Ifng, Il6, Gzmb concomitant with and an increase of Nos2, Ptgs2 mRNA levels." (PMID 28018318, 2016). "In our study, IL-6 levels correlated with viral titer throughout the course of infection and prophylactic treatment significantly reduced the IL-6 levels." (PMID 27110056, 2016). "Prior to infection, the baseline levels of IL‐6 and IL‐8 secretion were significantly higher in the HNE cells obtained from allergic subjects than in the cells obtained from non‐allergic subjects." (PMID 27957326, 2016). "Infected WT mice had increased TNF-α and IL-6 throughout the duration of infection, while the inflammatory cytokine response in β6 KO mice was less robust." (PMID 27505057, 2016). "For IL-6 secretion, earlier induction by A1142::Ref-K57orf13, from <4 h post-infection, was observed." (PMID 27550826, 2016). "CRP is an inflammatory marker and a typical acute phase reactant that increases with inflammation, infection, and trauma; it is produced in the liver in response to cytokines, such as interleukin-6." (PMID 27660715, 2016).
infection (continued). "In the livers of animals infected with HA-MARV, the pro-inflammatory cytokines TNF-α and IL-6, as well as the Th2 cytokines IL-4 and IL-5 and the Th1 cytokine IL-12, were all elevated early before decreasing over the course of infection." (PMID 27976688, 2016). "At 1 wk post infection, mRNA levels of Il6 in the spleen were increased in Il27ra−/− mice, similar to the serum; however, Il10 and Tnf mRNA levels were similar between WT and Il27ra−/− mice." (PMID 27259855, 2016). "In this study, inflammation was firstly observed in bronchiolar compartments, in association with viral replication in bronchiolar epithelial cells and the higher expression of IFNα and IL-6, early after infection." (PMID 27825367, 2016). "The absence of either TLR2 or TLR4 significantly reduced the production of TNFα and IL6 after 24 and 48 h of infection." (PMID 28119856, 2016). "In contrast to 17D-204, infection with the wild type Asibi virus reproduces remarkably human-like disease, accompanied by a substantial cytokine response with high levels of IL-6 and MCP-I." (PMID 27463517, 2016). "The transcription factor NF-κB is critical for the inducible expression of multiple cellular and viral genes involved in inflammation and infection including IL-6." (PMID 27999284, 2016). "We used 6 h of infection as the time to observe detectable IL-6 protein amounts to avoid cell death due to pneumococcal overgrowth which was observed at longer time points (MOI: 0.1)." (PMID 27597997, 2016). "A severe inflammatory reaction was detected by elevation of serum cytokines, including Interleukin (IL)1Ra, IL-6, and IL-8, after infection." (PMID 27855182, 2016). "With regards to immune profiles, patent infections of S. mansoni were strongly associated with young and adolescent cohorts, elevated SEA-specific IgG4, and systemic IL-6, IL-10 and IL-13." (PMID 27152725, 2016). "Concerning IL-6, the protein release was detected in supernatants of the cells of all donors after 3 h in the acute model of infection and after 9 h in the persistent infection one." (PMID 27446812, 2016). "As expected, compared to uninfected controls, SA infection resulted in the increased expression of IL-1β, IL-6, and CXCL2 and their levels were significantly lower in Pam3 pretreated retinal tissue." (PMID 26865111, 2016). "The gene expression of IL6 was the only one that was significantly induced due to the co-stimulation 30 h post-infection when directly compared to pbMEC, which were only treated with E. coli for 30 h." (PMID 27310007, 2016). "IL-6 is an integral cytokine mediator of the acute phase response to injury and infection, and can stimulate immune responses such as the activation of T cells proliferation." (PMID 27064787, 2016). "The expression of IL6 was downregulated in uninfected Caco-2 cells, and IL6 was neutrally expressed after S. Typhimurium SL1344 infection and significantly upregulated after S. Typhimurium ΔspeG infection." (PMID 27064787, 2016). "Consistently, we show here that infection with EcoHIV virus for 24 h induces several-fold increase in IL-6 secretion in primary astrocytes." (PMID 27287400, 2016). "The classically activated macrophages produce high levels of proinflammatory cytokines such as tumor necrosis factor-α (TNF-α), interleukin-1β (IL-1β), IL-6, and reactive oxygen to protect host against the infection." (PMID 27322250, 2016). "Levels of inflammatory cytokines IL-6 and IL-1β in the CSF at 21 h after infection were higher in rats infected with serotype 6B than 7F, suggesting an association between an exaggerated inflammatory response and worse outcome." (PMID 27009189, 2016). "Infection of hDFSCs with P. intermedia or T. forsythia results in increasing IL-6 concentration in the supernatant after 24 h." (PMID 27974831, 2016). "Expression of Il6 and Ccl5 declined after initial NTHi infection, whereas other cytokines showed sustained upregulation." (PMID 26611891, 2016).
infection (continued). "Although the production of proinflammatory cytokines (e.g., TNF-α and IL-6) by macrophages/microglia is essential in early host defense against infection, excessive accumulation of these cytokines disrupts systemic or CNS homeostasis." (PMID 27191001, 2016). "We developed IL-6 knocked-down and scramble (sc) control cells of A549 and H157 cell lines by lentiviral infection system, isolated CD133+ and CD133– sub-populations, and investigated the IL-6 role in self-renewal/growth of these cells." (PMID 26675547, 2016). "This infection decreased the migratory capacity of the hDFSCs by 50%, did not disturb hDFSC differentiation potential and provoked an increase in IL-6 and IL-8 secretion while leaving IL-10 levels unaltered." (PMID 27974831, 2016). "Infection with ALV-J strain HLJ09SH02 significantly induced IL-6 mRNA and protein levels in all three cell types." (PMID 27852059, 2016). "holarctica and ssp. mediasiatica infected co-cultures up to 72 h, IL-6 levels remained stable upon infection with the LVS strain." (PMID 26739172, 2016). "In our study, we evaluated cytokines produced in both the acute (IL-1α/β and TNF-α) and the chronic phases (IFN-γ, IL-10, and IL-6) of inflammation/infection and involved in the bone remodeling (IL-6)." (PMID 27478310, 2016). "At 12 h post-infection, IL-6 mRNA expression in the infected group was approximately 4-fold higher than in the control group (p < 0.01), with a similar trend exhibited for protein expression (p < 0.01)." (PMID 27852059, 2016). "IL-6 is a pro-inflammatory cytokine secreted by T-cells, which stimulates immune response, eg, during infection and after tissue damage leading to inflammation." (PMID 27106358, 2016). "It induced the release of neutrophil-mobilizing cytokine, including IL-6 and IL-8, to site of infection." (PMID 27855209, 2016). "At 4 h post-infection, the transcription levels of IL-10, IL-6 and TNFα were reduced in the legS2 infected monolayers as compared to the JR32 infected monolayers." (PMID 26741365, 2016). "In the process of control of the infection by mycobacteria, IL-12, IL-6, and TNF-α seem to have a primordial function." (PMID 27478636, 2016). "Infection significantly increased levels of the pro-inflammatory cytokine IL-6 at 24 hours after infection in the airways, which declined as the infection was cleared." (PMID 27273266, 2016). "At 29 days post-infection, Ifng, Gzmb, and Il6 mRNA levels strongly decreased whereas a strong up-regulation of Ptgs2 and in a lesser extent Nos2 and Ccl2 mRNA levels remained." (PMID 28018318, 2016). "First, during the acute phase of infection, on d7, when parasitaemia is growing but relatively low, IFNγ was the cytokine with the highest expression levels, followed by IL6 and IL12." (PMID 25890318, 2015). "As with IL-8 the IL-6 concentration in the media increased by threefold relative to control cells following 24 hr of infection." (PMID 26259872, 2015). "LCMV infection induced a very good titer of all the major proinflammatory cytokines (TNF, IL12p70, IL1β, IL-6) by day 7 that gradually decreased as infection proceeded." (PMID 26322025, 2015). "IL-8 concentrations increased significantly throughout the course of infection (p<0.001), with IL-1α and IL-6 demonstrating a trend in increasing concentration over time (p=0.936, p=0.191, respectively)." (PMID 26473163, 2015). "In patients with infection, levels remained elevated until 24 h in the case of IL-10 and until day 7 in the case of IL-6 and CRP, respectively." (PMID 25613713, 2015). "Expression of IL-6 is very low or undetectable at mid-gestation in normal pregnancy, but is induced in the uterus upon infection." (PMID 25961579, 2015). "Interleukin-8 (IL-8) is a pro-inflammatory mediating chemokine produced by macrophages in response to infection, while IL-6 is an inflammatory cytokine that also mediates fever." (PMID 26437779, 2015).